YWHAZ (tyrosine 3-monooxygenase/tryptophan 5-monooxygenase activation protein zeta)
Description:
Adapter protein implicated in the regulation of a large spectrum of both general and specialized signaling pathways. Binds to a large number of partners, usually by recognition of a phosphoserine or phosphothreonine motif. Binding generally results in the modulation of the activity of the binding partner. Promotes cytosolic retention and inactivation of TFEB transcription factor by binding to phosphorylated TFEB. Induces ARHGEF7 activity on RAC1 as well as lamellipodia and membrane ruffle formation. In neurons, regulates spine maturation through the modulation of ARHGEF7 activity (By similarity).
Synonyms: KCIP-1; 14-3-3-zeta; HEL-S-3; HEL-S-93; HEL4; POPCHAS; YWHAD
Tractability: Small molecule: a structure with a bound ligand is known; a high-quality ligand is known; it has a binding pocket of medium quality. PROTAC: ubiquitination databases record sites on it; its protein half-life has been measured; a small molecule that binds it is known.
Gene: Protein-coding gene on chromosome 8 (100,916,523 to 100,953,388, reverse strand). Ensembl gene ENSG00000164924.
Subcellular location: Cytoplasm; Melanosome
Subcellular location (Human Protein Atlas): Cytosol; Nucleoli rim; Nucleoplasm
Pathways (Reactome):
Signal Transduction: Deactivation of the beta-catenin transactivating complex; NOTCH4 Activation and Transmission of Signal to the Nucleus; Negative regulation of NOTCH4 signaling; RHO GTPases activate PKNs
Disease: SARS-CoV-1 targets host intracellular signalling and regulatory pathways; SARS-CoV-2 targets host intracellular signalling and regulatory pathways
Gene expression (Transcription): Regulation of localization of FOXO transcription factors
Immune System: Interleukin-3, Interleukin-5 and GM-CSF signaling; Rap1 signalling
Cell Cycle: Chk1/Chk2(Cds1) mediated inactivation of Cyclin B:Cdk1 complex
Developmental Biology: Transcriptional and post-translational regulation of MITF-M expression and activity
Hemostasis: GP1b-IX-V activation signalling
Metabolism of RNA: KSRP (KHSRP) binds and destabilizes mRNA
Programmed Cell Death: Activation of BAD and translocation to mitochondria
Vesicle-mediated transport: Translocation of SLC2A4 (GLUT4) to the plasma membrane
Gene Ontology:
Molecular function: cadherin binding; DNA-binding transcription factor binding; identical protein binding; phosphoserine residue binding; protein binding; protein kinase binding; protein phosphatase binding; protein sequestering activity; RNA binding; transmembrane transporter binding; ubiquitin protein ligase binding; protein domain specific binding
Biological process: cellular response to glucose starvation; establishment of Golgi localization; Golgi reassembly; negative regulation of innate immune response; negative regulation of protein localization to nucleus; negative regulation of TORC1 signaling; negative regulation of transcription by RNA polymerase II; protein phosphorylation; regulation of ERK1 and ERK2 cascade; regulation of protein stability; regulation of synapse maturation; signal transduction; intracellular protein localization; negative regulation of apoptotic process; angiogenesis; lung development; respiratory system process; synaptic target recognition; tube formation
Cellular component: blood microparticle; cytoplasm; cytosol; extracellular exosome; extracellular region; focal adhesion; glutamatergic synapse; melanosome; nucleus; vesicle; nucleoplasm; hippocampal mossy fiber to CA3 synapse
Genetic constraint (gnomAD): Loss-of-function variants: 0 observed, 30.69 expected, observed/expected ratio (o/e) 0, 90% interval 0 to 0.097. The upper end of that interval is the gene's LOEUF score, 0.097, which puts it in group 1 of 6, group 1 being the genes least tolerant of losing a copy. Missense variants: 79 observed, 282.03 expected, observed/expected ratio (o/e) 0.28, 90% interval 0.23 to 0.34. Synonymous variants: 87 observed, 99.71 expected, observed/expected ratio (o/e) 0.87, 90% interval 0.73 to 1.04.
Gene-disease validity (ClinGen):
ClinGen rates the evidence that YWHAZ causes each of these diseases.
complex neurodevelopmental disorder (autosomal dominant): Moderate. A disorder that involves more than one phenotype associated with the central nervous system, including but not limited to intellectual disability, autism, and seizures (epilepsy).
Homologues: Orthologues: chimpanzee YWHAZ (100% identical), dog YWHAZ (100% identical), guinea pig YWHAZ (100% identical), macaque YWHAZ (100% identical), pig YWHAZ (100% identical), rabbit YWHAZ (100% identical), mouse Ywhaz (99% identical), rat Ywhaz (99% identical), tropical clawed frog ywhaz (91% identical), Drosophila melanogaster 14-3-3zeta (81% identical), Caenorhabditis elegans par-5 (78% identical), Caenorhabditis elegans ftt-2 (75% identical). Paralogues in human: YWHAB (87% identical), YWHAQ (80% identical), YWHAG (76% identical), YWHAH (76% identical), SFN (71% identical), YWHAE (71% identical).
Diseases named in the same sentence as YWHAZ in open-access papers:
YWHAZ is named in the same sentence as 136 diseases in open-access papers, as found by Europe PMC text mining. Sharing a sentence is not in itself a finding about the gene and the disease. The quoted sentences say what the papers report.
gastric cancer (34 papers, 2012 to 2025). A primary or metastatic malignant neoplasm involving the stomach. "The miR-149–5p/YWHAZ axis, for example, has a special function in the progression of gastric cancer." (PMID 39293372, 2024). "A decreased YWHAZ expression inhibited cell proliferation and migration in gastric cancer cells, which frequently detected YWHAZ protein was upregulated." (PMID 36834640, 2023). "Previous study has proved that LUCAT1 promotes the proliferation and metastasis of gastric cancer by regulating miR-134-5p/YWHAZ axis." (PMID 37550755, 2023). "One study found that G3BP1 interacts with YWHAZ to isolate Bax in the cytoplasm, thereby enhancing chemotherapy resistance in gastric cancer." (PMID 37179344, 2023). "Meanwhile, overexpression of the YWHAZ gene has been demonstrated to be a prognostic and therapeutic target in gastric cancer." (PMID 35547358, 2022). "YWHAZ strengthens the gastric cancer cells growth ability by suppressing cell apoptosis and autophagy." (PMID 33968726, 2021). "Whereas, slightly higher YWHAZ expression was also found in gastric cancer tissues infected with H. pylori." (PMID 33718136, 2021). "To validate function of YWHAZ, we then examined the expression of YWHAZ in a panel of gastric cancer cell lines." (PMID 33718136, 2021). "We found that G3BP1 mRNA levels were positively correlated with YWHAZ mRNA levels in gastric cancer patients by data mining the TCGA database (n = 233, r = 0.379, P < 0.001) and the GEO database (n = 80, r = 0.503, P < 0.001)." (PMID 32989225, 2021). "We found that only YWHAZ displayed a significant correlation with the survival of gastric cancer patients who received postoperative chemotherapy." (PMID 32989225, 2021). "Cell lines and animal experiments were performed to investigate proliferation and metastasis of miR-193a and YWHAZ in gastric cancer cell lines." (PMID 33718136, 2021). "Taken together, these results suggested that YWHAZ, a miR-193a target, induced cell proliferation and invasion in gastric cancer cell lines." (PMID 33718136, 2021). "Consistent with a previous report, YWHAZ was highly expressed in gastric cancer tissues compared with adjacent normal tissues from Zhongshan cohort patients (n = 455, P < 0.001)." (PMID 32989225, 2021). "Sponging functions of circular RNAs, circ-SERPINE2 and YWHAZ, have been reported in a recent study to influencing miR-375 function in gastric cancer." (PMID 34660323, 2021). "Our mechanistic exploration showed that G3BP1 co-localised with YWHAZ in the cytoplasm and physiologically interacted with YWHAZ in gastric cancer cells." (PMID 32989225, 2021). "Further analysis of Zhongshan cohort patients by IHC staining demonstrated that the protein expression of G3BP1 and that of YWHAZ were also positively correlated in human gastric cancer (n = 455, r = 0.464, P < 0.001)." (PMID 32989225, 2021). "Bisulfite pyrosequencing and tissue microarray were performed to investigate the promoter methylation of miR-193a and expression of STAT3, YWHAZ in patients with gastritis (n = 8) and gastric cancer (n = 71)." (PMID 33718136, 2021). "Meanwhile, knockdown of YWHAZ or Bax had little effect on SGs formation in gastric cancer cells, which indicates that G3BP1/YWHAZ/Bax pathway exerts anti-apoptosis and chemoresistance roles in gastric cancer via an SG-independent mechanism." (PMID 32989225, 2021). "Tissue microarray also showed a positive trend between STAT3 and YWHAZ expression in gastric cancer patients (n = 60)." (PMID 33718136, 2021). "Epigenetic silencing of miR-193a led to overexpression of the adapter protein and metastatic regulator YWHAZ, resulting in gastric cancer progression." (PMID 33718136, 2021). "Taken together, in this study, G3BP1 was revealed to govern gastric cancer apoptosis and to play a pivotal role in gastric cancer chemoresistance through mediating SGs formation or via an SG-independent mechanism: the G3BP1/YWHAZ/Bax axis." (PMID 32989225, 2021).
gastric cancer (continued). "YWHAZ knockdown by specific siRNAs, has been shown to inhibit the proliferation, migration, and invasion of YWHAZ-overexpressing gastric cancer cells." (PMID 31388092, 2019). "Moreover, miR-375 expression was inversely correlated (r = −0.629) with the expression of YWHAZ (14-3-3ζ), a member of the 14-3-3 family of proteins, which has been implicated in the initiation and progression of cancers and is a potential biomarker for gastric cancer." (PMID 30258124, 2018). "YWHAZ promotes the progression of gastric cancer, prostate cancer, and hepatocellular carcinoma." (PMID 37496025, 2023). "Moreover, recent evidence suggests that G3BP1 inhibits gastric cancer cell apoptosis via the YWHAZ/Bax axis." (PMID 37179344, 2023). "Additionally, miR-1-3p inhibited the growth of colorectal cancer and gastric cancer cells through controlling YWHAZ-mediated EMT." (PMID 36555545, 2022). "Further expression microarray and bioinformatics analysis identified YWHAZ as one of the target of miR-193a in AGS gastric cancer cells, such that depletion of YWHAZ reduced migration in AGS cells, while its overexpression increased invasion in MKN45 cells in vitro and in vivo." (PMID 33718136, 2021). "The expression of G3BP1 and YWHAZ could predict the adjuvant chemotherapy benefit in gastric cancer patients." (PMID 32989225, 2021). "As YWHAZ was previously found to be involved in cancer metastasis, overexpression of YWHAZ could enhance gastric cancer invasion in vitro and in vivo." (PMID 33718136, 2021). "Taken together, these results suggested that miR-193a targets YWHAZ in gastric cancer cell lines." (PMID 33718136, 2021). "To confirm the role of miR-193a and YWHAZ in gastric carcinogenesis, we analyzed promoter methylation of miR-193a in tissue samples obtained from gastritis (n = 8), and paired tumor adjacent normal and gastric cancer (n = 11) by bisulfite pyrosequencing." (PMID 33718136, 2021). "In human gastric cancer cells (AZ521, MGC-803), circ-SERPINE2 could competitively bind to miR-375 to affect the transcription of YWHAZ, thereby promoting the development of gastric cancer." (PMID 34494089, 2021). "Further investigation showed that YWHAZ was positively correlated with G3BP1 expression in gastric cancer patients and that high expression of both G3BP1 and YWHAZ was associated with the worst prognosis in gastric cancer patients who received ACT." (PMID 32989225, 2021). "Furthermore, restoration of miR-193a in gastric cancer cell suppressed proliferation and migration in vitro, probably due to suppression of YWHAZ, which is found to be a target of miR-193a." (PMID 33718136, 2021). "Finally, miR-375 targets YWHAZ (14-3-3ζ) which regulates proliferation, apoptosis, migration, and invasion in gastric cancer cell lines." (PMID 31934893, 2020). "The mechanism for miR-488-3p down-regulation are complex, recent studies have provided new biological explanation for the regulation of miRNAs, in which demonstrated circ‐SERPINE2 can promote cell proliferation by sponging miR‐375 and regulating YWHAZ expression in gastric carcinoma cells." (PMID 32231744, 2020). "Furthermore, a growing number of studies have proposed that elevated YWHAZ expression was correlated with poor prognosis in prostate cancer 44, ICC 48, and gastric carcinoma 21, implying that YWHAZ was tightly associated with the survival of cancer patients." (PMID 32127952, 2020). "In addition, we found through a gene co-expression analysis that G3BP1 could be co-expressed with YWHAZ in gastric cancer." (PMID 32989225, 2021). "Importantly, high YWHAZ expression indicated a poor outcome for gastric cancer patients." (PMID 32989225, 2021). "Suppression of miR-193a might induce YWHAZ overexpression, resulting in gastric cancer metastasis." (PMID 33718136, 2021). "Therefore, we speculated that G3BP1 co-expression and binding with YWHAZ could modulate the interaction between YWHAZ and Bax in gastric cancer cells." (PMID 32989225, 2021).
gastric cancer (continued). "In gastric cancer, circ-SERPINE2 sponges miR-375 and regulates YWHAZ (tyrosine 3-monooxygenase/tryptophan 5-monooxygenase activation protein zeta) expression to promote the development of gastric cancer." (PMID 35440286, 2022). "Then, we investigated the correlation between YWHAZ expression and G3BP1 expression in human gastric cancer samples." (PMID 32989225, 2021). "We also performed tissue microarray to determine the correlation between STAT3 and YWHAZ expression in gastric cancer tissue samples (n = 60), showing a positive trend of STAT3 and YWHAZ (r = 0.208)." (PMID 33718136, 2021). "Three target genes (EZH2, YWHAZ and RUNX1) were upregulated in gastric cancer compared to normal gastric mucosa." (PMID 30258124, 2018). "Similarly, miR-1-3p has been shown to inhibit gastric cancer progression by targeting CENPF, and to suppress colorectal cancer cell proliferation and metastasis by targeting YWHAZ and regulating EMT." (PMID 39062049, 2024). "The YWHAZ gene has been described in multiple cancers including non-small lung cancer, hepatocellular carcinoma, gastric cancer, bladder cancer, and in breast cancers." (PMID 34350123, 2021). "To address the molecular mechanisms by which the co-expression and co-operative function of G3BP1 and YWHAZ act in gastric cancer, we initially performed immunofluorescence assay to detect the intracellular localisation of G3BP1 and YWHAZ in gastric cancer cells." (PMID 32989225, 2021).
breast carcinoma (28 papers, 2012 to 2024). "Overexpression of YWHAZ in breast cancers has been associated with chemoresistance to anthracyclines particularly associated with metastatic recurrence." (PMID 34350123, 2021). "Although there is no information about the function of YWHA, but upregulation of one member of YWHAZ (also known as 14-3-3ζ) had been found associated with poor clinical outcome in breast cancer." (PMID 32190687, 2020). "Finally, the increase in expression of the genes CCNE1, FANCI, RFC4, CDC6, and YWHAZ associated with poor prognosis in luminal A breast cancer (OS, HR:2.54, CI 1.69–3.82, log rank p = 3.6 × 10−6; RFS, HR:1.84, CI 1.53–2.22, log rank p = 6.5 × 10−11)." (PMID 33925616, 2021). "High expression of YWHAZ has been associated with poor clinical outcome in ER+ breast cancer." (PMID 22719901, 2012). "Similarly, YWHAZ overexpression was significantly associated with reduced disease-free survival/overall survival and earlier time to disease recurrence, and death in breast cancer by combining with elevated levels of Akt, FOXM1, ErbB2, LOC441453 and LAPTM4B 31, 32, 35, 36, 39, 78-80." (PMID 32127952, 2020). "To find co-function or regulatory relationships for the putative PPIs between SOD1 and YWHAE or YWHAZ, we used a breast cancer quantitative proteome database to analyze latent correlations of their protein expression profiles." (PMID 36834640, 2023). "Studies indicate that YWHAZ is frequently increased in malignancies such as hepatocellular carcinoma, colorectal cancer, lung cancer, and breast cancer." (PMID 36388433, 2022). "Nineteen genes from these gene sets were identified to be amplified and upregulated in breast cancer but only five of them NBN, PRKDC, RFWD2, UBE2T, and YWHAZ meet criteria in all breast cancer molecular subtypes." (PMID 33925616, 2021). "Increased relative gene expression and copy number variation of CCND1 and YWHAZ was observed in MDA-MB-468 breast cancer cells and silencing PGRMC1 reduced the expression of these genes." (PMID 34350123, 2021). "A growing body of literature has proved that YWHAZ is overexpressed in a wide range of tumor types, such as lung cancer, breast cancer, colorectal cancer, and HCC." (PMID 34977001, 2021). "In in vivo studies, YWHAZ overexpression in FVB mice accelerated the progression of mammary tumors through EMT, angiogenesis promotion and apoptosis inhibition." (PMID 32127952, 2020). "Remarkably, the expression of YWHAZ is inversely correlated with the level of miR-451 in human breast cancer samples." (PMID 28981108, 2017). "Previous studies documenting YWHAZ upregulation and a poor clinical outcome in tamoxifen treated breast cancer patients imply it to be a marker of poor prognosis in women with ER-positive breast cancers." (PMID 22937096, 2012). "Interestingly, some other molecules located in 8q22, including LAPTM4B and YWHAZ, were also identified as key functional molecules for anthracycline resistance and breast cancer recurrence." (PMID 38862581, 2024). "Meanwhile, the opposite correlations between YWHAE and YWHAZ with SOD1 from the breast cancer proteome data imply that these PPIs might drive different metabolic impacts in breast cancer development." (PMID 36834640, 2023). "In paclitaxel (PTX)-resistant breast cancer, circ_0069094 is highly expressed, and inhibiting circ_0069094 could restore sensitivity to PTX in breast cancer with PTX resistance by regulating the miR-136-5p/YWHAZ axis." (PMID 38186573, 2023). "More and more studies have shown that YWHAZ is upregulated in breast cancer, ovarian cancer, G2 endometrial adenocarcinoma, prostate cancer, and other types of genitourinary tumors and that it participates in cell growth, cell cycle, apoptosis, migration, and invasion." (PMID 33664765, 2020).